LBP (lipopolysaccharide binding protein)
Diseases named in the same sentence as LBP in open-access papers (continued):
Sharing a sentence is not in itself a finding about the gene and the disease.
Salmonella Infections (6 papers, 2019 to 2023). Infections with bacteria of the genus SALMONELLA. "Enrichment of lipopolysaccharide-binding protein was identified in the Salmonella infection pathway (corrected p = 0.079), NF-kappa B (corrected p = 0.044), peroxisome proliferator-activated receptors (PPAR), and Toll-like receptor (corrected p = 0.088) signaling pathways." (PMID 35479637, 2022). "The DEPRGs were particularly associated with Salmonella infection, Yersinia infection, tuberculosis, CLEC7A/inflammasome pathway, viral protein interaction with cytokine and cytokine receptor, transfer of LPS from LBP carrier to CD14, and neutrophil degranulation." (PMID 35991562, 2022). "We further confirmed the LBP (Lipopolysaccharide Binding Protein) and BPI (Bactericidal Permeability Increasing Protein) genes, among 11 genes showing selection signals in the Salmonella infection pathway." (PMID 31440273, 2019). "We uncovered genomic regions of selective sweeps in the LBP and BPI genes (Salmonella infection) and the TTN and ITGB6 genes (cardiomyopathy), among several candidate genes." (PMID 31440273, 2019). "The Salmonella infection upregulated LBP, CD14, TLR4, and LBP in the colon." (PMID 38003758, 2023). "Therefore, we further investigated patterns of nucleotide diversity, linkage disequilibrium, haplotype diversity, and Fst of LBP, BPI, ITGB6, and TTN genes, among KNG’s candidate genes enriched in Salmonella infection and cardiomyopathy pathways." (PMID 31440273, 2019). "In mice, it was identified that LBP is essential for the rapid induction of an inflammatory response by small amounts of LPS or Gram-negative bacteria during the survival of intraperitoneal Salmonella infections." (PMID 31572451, 2019).
Ascites (5 papers, 2010 to 2025). Accumulation of fluid in the peritoneal cavity (between the layers of the peritoneum that lines the abdomen). "Their findings revealed that the serum microbiome of individuals with ascites exhibited elevated levels of lipopolysaccharide-binding protein, a known indicator of microbial translocation." (PMID 40565268, 2025). "High serum LBP levels in the cirrhotic patients with ascites developing severe bacterial infection were significantly higher than those in patients with normal LBP levels (32.4% vs. 8.0%; RR: 4.49)." (PMID 32280697, 2020). "In the absence of overt infections, norfloxacin also normalizes elevated proinflammatory cytokine levels and increases vascular resistance in patients with ascites who present with a high lipopolysaccharide-binding protein (LBP) level." (PMID 20886039, 2010).
Cachexia (5 papers, 2018 to 2022). Severe weight loss, wasting of muscle, loss of appetite, and general debility related to a chronic disease. "A recent study shed light on the possible role of the gut microbiota in human cachexia by showing that cachectic patients had higher serum levels of bacterial lipopolysaccharide binding protein." (PMID 31731747, 2019). "In addition, the level of lipopolysaccharide-binding protein (LBP) in serum has been suggested as a biomarker of cachexia." (PMID 34002024, 2021). "In addition, we found out that serum LBP was predictive of cachexia and death." (PMID 29719601, 2018). "Indeed, lipopolysaccharide-binding protein (LBP), a marker of bacterial translocation, is increased in C26-bearing mice and correlates with cachexia manifestation, whereas it is a predictor of overall survival, appetite, anorexia, and cachexia manifestation in lung and colon cancer patients." (PMID 36158184, 2022).
dengue (5 papers, 2015 to 2023). "Previous studies shown that abnormal inflammasome and monocyte activation play a pathogenic role in the development of dengue, supported by evidence based on clinical samples in which IL-18, LBP and sCD14 are elevated in patients with severe dengue." (PMID 36091000, 2022). "Here we observed that the severity of dengue disease was associated with aberrant activation of monocyte or macrophages as evidenced by elevation of plasma IL-18, sCD14 and LBP particularly at the febrile phase." (PMID 28569153, 2017). "We found that the LBP and sCD14 at febrile phase were significantly associated with the severity of dengue disease." (PMID 28569153, 2017). "To determine if other biomarkers of monocyte and macrophage activation had any association with the severity of dengue disease, we assessed plasma levels of LPS binding protein (LBP), sCD14, sCD163, MIF, MCP-1 and MIP-1b in the three study groups." (PMID 28569153, 2017). "Our multivariate model showed that all the three IL-18, LBP and sCD14 markers at febrile phase were independently associated with the more severe form of dengue disease; whilst at defervescence phase, only was IL-18 was found to be independently associated with severity of dengue disease." (PMID 28569153, 2017). "Given that the elevation IL-18, LBP and sCD14 among patients with severe form of dengue disease, our findings suggest a pathogenic role for an aberrant inflammasome and monocyte activation in the development of severe form of dengue disease." (PMID 28569153, 2017). "Extending from these study, we sought to determine the values of MT markers i.e. LBP and sCD14 in predicting severity of dengue disease." (PMID 28569153, 2017). "Lipopolysaccharide (LPS) and lipopolysaccharide binding protein (LBP) are another set of molecules that have higher levels in dengue cases compared to healthy controls and in clinically severe cases compared to dengue fever, which could indicate their usefulness as a predictor of severity." (PMID 36848385, 2023).
gastric cancer (5 papers, 2020 to 2025). A primary or metastatic malignant neoplasm involving the stomach. "LBP single nucleotide polymorphisms (SNPs) have been shown to be associated with colorectal cancer, gastric cancer and glioma." (PMID 36157452, 2022).
malaria (5 papers, 2011 to 2024). Malaria is a serious and sometimes fatal disease caused by a parasite that commonly infects a certain type of mosquito which feeds on humans. "Out of the six proteins, three were identified as showing increased levels (CRP, CSF1, LBP) in malaria patients compared to controls while the remaining three displayed decreased levels (CCL5, CTSD, SPARC)." (PMID 30442134, 2018). "HZ coated with sera from mild and severe malaria patients showed a higher level of LBP compared to control sera." (PMID 22028888, 2011). "More importantly, we report herein for the first time the up-regulation of LPS binding protein (LBP) in malaria." (PMID 22028888, 2011). "Of particular interest is LPS binding protein (LBP), which is reported herein for the first time in the context of malaria." (PMID 22028888, 2011). "Our findings, in the context of malaria, also suggest that LBP in conjunction with other identified proteins can be used as an important malaria biomarker." (PMID 22028888, 2011). "The peptides of LBP, apolipoprotein E, serum amyloid A, alpha-1-antitrypsin and hemoglobin subunit alpha were found to be significantly higher in samples from malaria patients." (PMID 22028888, 2011). "The level of LBP measured was significantly increased in malaria patients." (PMID 22028888, 2011). "Six representative examples, showing both increased (ADSSL1, CEBPA, CRP, LBP) and decreased protein levels (CCL5, SPARC) in malaria patients compared to controls are shown in." (PMID 30442134, 2018).
non-alcoholic fatty liver disease (5 papers, 2017 to 2026). "Core tip: This is the first study simultaneously measuring two surrogate endotoxemia markers, lipopolysaccharide-binding protein (LBP) and EndoCab IgG, in biopsy-proven nonalcoholic fatty liver disease (NAFLD) patients in order to assess for relationships with the histological features of NAFLD." (PMID 28216979, 2017). "YCHD combined with probiotics significantly ameliorates symptoms of non-alcoholic fatty liver disease, reduces levels of blood lipids and liver enzymes, prevents hepatocyte destruction, and notably decreases levels of lipopolysaccharide-binding protein (LBP), total bile acid (TBA) and TNF-α." (PMID 39170703, 2024).
ovarian carcinoma (5 papers, 2020 to 2025). A malignant neoplasm originating from the surface ovarian epithelium. "Zhang and colleagues identified LBP (lipopolysaccharide-binding protein), GSN (gelsolin), FGA (fibrinogen alpha chain), and FGG (fibrinogen gamma chain) as potential diagnostic exosomal proteins for ovarian cancer, with FGA found to be the most promising diagnostic marker." (PMID 34571921, 2021). "Exosome expression of lipopolysaccharide-binding proteins (LBP) andsoluble E-cadherin have also been used to distinguish NSCLC and ovarian cancer cells withmetastatic and non-metastatic phenotypes." (PMID 32257533, 2020).
tuberculosis (5 papers, 2013 to 2026). A chronic, recurrent infection caused by the bacterium Mycobacterium tuberculosis. "We performed cluster analysis for the top 5 KEGG pathways to explore the association of genes such as LBP, CSF3, and FCGR2A with leishmaniasis, hematopoietic cell, strain, tuberculosis, and osteoclast differentiation." (PMID 33973530, 2021). "LPS, sCD14, LBP, EndoCAB and TFF3 showed significant trends in patients with positive biomarkers of tuberculosis dissemination." (PMID 42282041, 2026). "In addition, among these differential proteins, LBP, CD36, and MHC-I attracted our interest and these three molecules are closely related to the infection of tuberculosis, especially CD36." (PMID 35069505, 2021).
Abdominal obesity (4 papers, 2013 to 2024). Excessive fat around the stomach and abdomen. "A moderate low-calorie diet together with increased physical activity after 2 and 12 months improved enteral permeability by decreasing chemerin and lipopolysaccharide-binding protein (LBP) levels in adolescents with abdominal obesity." (PMID 38675438, 2024).
Allergy (4 papers, 2013 to 2021). An allergy is an immune response or reaction to substances that are usually not harmful. "Further prospective studies are warranted to confirm the role of LBP-associated dysfunction of innate immunity in allergic sensitization and allergic diseases." (PMID 33495502, 2021). "We aimed to determine the association of serum LBP level with allergic sensitization and self-reported allergic diseases and to explore the possible mechanisms underlying this association." (PMID 33495502, 2021). "Other allergy-induced gene expression changes were confirmed by qPCR, including increased levels of tumor necrosis factor receptor superfamily member 23 and lipopolysaccharide-binding protein." (PMID 23915208, 2013). "Based on their association with allergy and the protein fold change (more than 1.1 or less than 0.9) between ATI responders and non-responders, four potential genes (MUC5B, LBP, C4BPB, LTA4H) were identified as potential biomarkers that indicate an effective AIT." (PMID 33329520, 2020).
colorectal cancer (4 papers, 2021 to 2025). A primary or metastatic malignant neoplasm that affects the colon or rectum. "SNORA71A knockdown in HT-29 cells led to significant inhibition of cell migration and invasion ability, which targeted LBP to participate in NAFLD in colorectal cancer cells." (PMID 38069077, 2023).
Crohn disease (4 papers, 2008 to 2024). A gastrointestinal disorder characterized by chronic inflammation involving all layers of the intestinal wall, noncaseating granulomas affecting the intestinal wall and regional lymph nodes, and transmural fibrosis. "We have previously shown that LBP positively correlated with CRP under inflammatory conditions (~1700 DBS samples collected during infections, vaccinations, surgery, intense exercise, and Crohn’s disease)." (PMID 39458532, 2024).
multiple sclerosis (4 papers, 2022 to 2026). A progressive autoimmune disorder affecting the central nervous system resulting in demyelination. "In this sense, studies from our research group conclude that MLT decreases intestinal dysbiosis in mice with experimental autoimmune encephalomyelitis (EAE), the animal model of multiple sclerosis, through the decrease of LPS and its binding protein (LBP)." (PMID 39382703, 2024). "These patients also had significantly higher levels of lipopolysaccharide-binding protein and mannose-binding lectin compared to HC suggesting the compromised gut barrier function in multiple sclerosis leading to higher level of microbial translocation in these patients." (PMID 41766816, 2026).
non-small cell lung carcinoma (4 papers, 2020 to 2022). A group of at least three distinct histological types of lung cancer, including non-small cell squamous cell carcinoma, adenocarcinoma, and large cell carcinoma. "Interestingly, LBP was found to be abundant in circulating exosomes of non-small cell lung cancer patients with metastatic disease, thus suggesting that increased circulating LBP might be associated with a more aggressive disease." (PMID 33562105, 2021). "Further studies also revealed that LBP in exosomes was able to effectively distinguish between patients with metastatic and patients with non-metastatic non-small cell lung cancers, but the underlying mechanism is still unknown." (PMID 32793465, 2020).
pancreatitis (4 papers, 2023 to 2025). Inflammation of the pancreas. "Patients with pancreatitis and cholangiosepsis exhibited similar plasma LBP levels compared to all other patients (p = 0.820)." (PMID 39997462, 2025). "Amylase, lipase, and lipopolysaccharides-binding protein (LBP) in serum were measured to assess the severity of pancreatitis." (PMID 37892502, 2023). "Gut permeability biomarkers (FABP2, LBP, and zonulin) did not change, but were associated with comorbid pathologies (alcohol liver disease and pancreatitis)." (PMID 38792318, 2024).
Parkinson disease (4 papers, 2015 to 2023). A progressive degenerative disorder of the central nervous system characterized by loss of dopamine producing neurons in the substantia nigra and the presence of Lewy bodies in the substantia nigra and locus coeruleus. "Overall, the remarkable reversal of amyloid fibrin formation by LBP addition to the plasma of Parkinson’s Disease patients firstly present a novel strategy for treating PD-associated- coagulopathies and secondly implies strongly that LPS is naturally pre-existing in said plasma." (PMID 29494603, 2018).
rheumatoid arthritis (4 papers, 2008 to 2023). A chronic, systemic autoimmune disorder characterized by inflammation in the synovial membranes and articular surfaces. "This study concluded that the presence of anti-lipopolysaccharide binding protein antibodies could become markers not only for the diagnosis of rheumatoid arthritis, but also for defining its severity." (PMID 37373476, 2023).
sarcoidosis (4 papers, 2023 to 2026). Sarcoidosis is a multisystemic disorder of unknown cause characterized by the formation of immune granulomas in involved organs. "Serum zinc finger protein 687 (ZNF688), ADP-ribosylation factor GTPase-activating protein 1 (ARFGAP1), CD14, and LBP (lipopolysaccharide-binding protein) have been identified as validated biomarkers for differentiating sarcoidosis from healthy control." (PMID 38250062, 2023). "Additionally, some studies compared TED with other inflammatory conditions, such as non-specific orbital inflammation, sarcoidosis, and granulomatosis with polyangiitis, or grouped patients based on factors like smoking status and serum lipopolysaccharide-binding protein levels." (PMID 39664569, 2024).
AIDS (3 papers, 2008 to 2026). A syndrome resulting from the acquired deficiency of cellular immunity caused by the human immunodeficiency virus (HIV). "Serum levels of microbial translocation markers, including FABP2, LPS-binding protein (LBP), haptoglobin, sCD14, endotoxin core antibody (EndoCab) IgM, and markers of macrophage activation, such as sCD163, are associated with AIDS-NHL risk." (PMID 39324141, 2024). "AIDS subjects with IV heroin or ethanol abuse had higher LPS and LBP levels compared to those with no substance abuse." (PMID 18575590, 2008). "We measured plasma levels of LBP and EndoCAb in AIDS patients with and without NCI and uninfected controls, and found that LBP levels were significantly higher in AIDS patients compared to uninfected subjects and correlated positively with plasma LPS." (PMID 18575590, 2008).
alcoholic hepatitis (3 papers, 2015 to 2025). Acute hepatitis resulting from ingestion of alcohol. "Intestinal barrier dysfunction can further contribute to the occurrence of alcoholic hepatitis by acting on the gut-liver axis, triggering inflammatory cascade reactions, and aggravating liver inflammation and LBP levels." (PMID 37795292, 2023). "In another reports, CRP levels were higher in patients with SIRS, infection, or alcoholic hepatitis and CRP was the most useful diagnostic marker of infection compared with other acute phase reactants such as the procalcitonin, lipopolysaccharide-binding protein, sCD14." (PMID 26498833, 2015).
alcoholic liver diseases (3 papers, 2023 to 2024). A disorder caused by damage to the liver parenchyma due to alcohol consumption. "Patients with alcoholic liver disease have a higher composition ratio of Streptococcus in the fecal flora, intestinal permeability, and blood LBP concentration compared to healthy subjects." (PMID 36837869, 2023).
asthma (3 papers, 2021 to 2023). "In summary, this study demonstrates considerable changes in circulating immune cell subset abundance during an acute asthma exacerbation, which is accompanied by differential gene expression and modulation of signalling networks, some of which are driven by LPS/LBP, glucocorticoids and TGFB1." (PMID 37438758, 2023).
cognitive decline (3 papers, 2021 to 2024). "This is in contrast to the association of plasma LPS in 36 individuals and plasma LBP in 636 individuals with AD as well as the independent association of plasma LPS with cognitive decline in 127 individuals." (PMID 37605096, 2024). "Levels of LPS-binding protein (LBP) and soluble CD14 (sCD14), the markers of leaky gut, are markedly higher in older adults and linked to age-associated physical and cognitive decline and increased risk of heart failure." (PMID 38329121, 2024). "As already mentioned, our assessments of the intestinal barrier were limited to measurements of serum IFABP and LBP which may not accurately represent the type of barrier dysfunction that precedes cognitive decline." (PMID 33661922, 2021).
colon cancer (3 papers, 2020 to 2025). "We developed and validated a five-immune gene model of colon cancer, including LBP, TFR2, UCN, UTS2, and MC1R." (PMID 32375704, 2020). "Similarly, cachectic mice bearing colon tumors showed higher expression of gut epithelial claudins (indicating disrupted tight junction regulation) and evidence of bacterial translocation with elevated serum LPS-binding protein (LBP)." (PMID 40572244, 2025).
HIV-1 infection (3 papers, 2018 to 2021). The type species of lentivirus and the etiologic agent of acquired immunodeficiency syndrome (AIDS). "In our current study, significantly high levels of pro-inflammatory cytokine sCD14, sCD163, IL-6, and LBP were detected in SC prior to HIV-1 infection compared to NC (p<0.05)." (PMID 34879869, 2021). "Circulating LBP levels correlate positively with plasma sCD14 levels during chronic HIV-1 infection." (PMID 32903610, 2020). "Furthermore, plasma inflammatory cytokine levels of sCD14, sCD163, interleukin 6, and lipopolysaccharide binding protein were significantly higher in SC with p<0.05 before HIV-1 infection compared to NC." (PMID 34879869, 2021). "Paradoxically, high levels of plasma sCD14 were found in the Portuguese HIV-2-infected cohort, as well as a significant activation of monocytes and DC, with high levels of HLA-DR and CD86 expression, like during HIV-1 infection, but LBP levels were similar to those of controls." (PMID 32903610, 2020).